Y_RNA (Y RNA )
Gene: Miscellaneous RNA gene on chromosome 14 (31,244,761 to 31,244,861, forward strand). Ensembl gene ENSG00000202402.
Homologues: Orthologues: chimpanzee Y_RNA (99% identical). Paralogues in human: RNY3 (93% identical), Y_RNA (92% identical), Y_RNA (90% identical), RNY3P1 (89% identical), Y_RNA (89% identical), Y_RNA (88% identical), Y_RNA (87% identical), Y_RNA (86% identical), Y_RNA (85% identical), RNY3P14 (84% identical), RNY3P9 (84% identical), Y_RNA (84% identical), and 97 more.